AQP3 (aquaporin 3 (Gill blood group))
Diseases named in the same sentence as AQP3 in open-access papers (continued):
Sharing a sentence is not in itself a finding about the gene and the disease.
Constipation (33 papers, 2016 to 2025). Infrequent or difficult evacuation of feces. "This is consistent with the AQP3 mRNA expression results and immunohistochemical analysis, suggesting that the overexpression of AQP3 in the constipation model is closely associated with the development of constipation." (PMID 41323823, 2025). "AQP3 is abundantly present in the colon, and its elevated expression increases water reabsorption, thereby causing constipation." (PMID 38634140, 2024). "It has been reported that the increase of AQP3 in colon is associated with the development of constipation in rats." (PMID 31877639, 2019). "This suggests that the overexpression of AQP3 in the constipation model may be associated with the development of constipation." (PMID 41323823, 2025). "The modulation of SCFA synthesis and AQP-3 expression by the H. rhamnoides fruit extract suggests a plausible direction to be pursued to understand the mechanisms underlying the traditional use of sea buckthorn as a constipation remedy." (PMID 41227770, 2025). "AQP3 is expressed primarily in intestinal mucosal epithelial cells, which facilitate the transport of water from the intestinal lumen to the cellular space, accelerate water translocation, and are directly linked to the development of constipation." (PMID 39684522, 2024). "It should be noted that the laxative effects of Maren pills or Pekinenin C in alleviating constipation may be associated with the increased expression of AQP3 via nuclear factor κB (NF-κB) signal pathway." (PMID 38089478, 2023). "AQP3 is involved in water absorption in the colon and is closely associated with constipation." (PMID 37047557, 2023). "We investigated the laxative effects and mechanisms of PCP-g in a murine model of sucralfate-induced constipation by analyzing the expression of key factors within the cAMP/PKA/AQP3 signaling pathway and TJPs." (PMID 40727692, 2025). "In the constipation mouse model, the expressions of AQPs have changed, including upregulated AQP3, AQP4, and AQP8, and downregulated AQP9." (PMID 40807605, 2025). "In this study, we aimed to investigate the underlying mechanism of SHTC on chemotherapy-induced constipation through regulating of gut microbiota and PI3K/AKT/AQP3 signaling pathway." (PMID 40708926, 2025). "Our findings indicated that SHTC effectively relieved 5-FU-induced constipation in mice, mainly by regulating homeostasis of gut microbiota and activating PI3K/AKT/AQP3 pathway, making it a potential protective agent against chemotherapy-induced constipation." (PMID 40708926, 2025). "Previous research reported that rats with constipation had significantly higher levels of AQP3 protein expression in their intestinal tissues, which affected water reabsorption in the colon and reduced fecal water content." (PMID 40458796, 2025). "Changes in AQP3 levels can affect water absorption, influencing intestinal water metabolism and contributing to constipation." (PMID 39963403, 2025). "The AQP3 protein level decreased with constipation induction and was significantly lower than that in the CON in proportion with the lactitol-administered dose (p < 0.01, p < 0.001, and p < 0.001, respectively)." (PMID 38998634, 2024). "Similar pattern of increased AQP3 expression was found while using diphenoxylate hydrochloride to induce constipation of rats." (PMID 38089478, 2023). "For example, AQP3 mRNA expression in the colon was upregulated with increasing serotonin (namely, 5-hydroxytrypamine, 5-HT) secretion in constipation-rats induced by morphine." (PMID 38089478, 2023). "It increases the level of AQP3 in the intestine, and finally alleviates constipation by increasing the content of fecal water and the small intestinal propulsion rate." (PMID 35573767, 2022). "The results of the present study in MP-induced constipation ICR mice showed partial agreement with previous results which reported that AQP3 expression was decreased or down-regulated in the colon of constipation rats." (PMID 34072552, 2021).
Constipation (continued). "Since AQPs expression and c‐Kit/SCF signaling pathway play an important role in treating constipation, thus, protein expressions of AQP3 and c‐Kit were detected and analyzed." (PMID 34136194, 2021). "Conversely, AQP3 expression levels were enhanced in the morphine-induced constipation model and morphine treated cancer patients with severe constipation." (PMID 34072552, 2021). "Colons of the Lop treated model with slow transit constipation show increased levels of AQP3 expression, but a reverse pattern was detected in the constipation model." (PMID 34072552, 2021). "In this study, we also found that Maren pills can upregulate the expression of PKA and CFTR proteins, which is consistent with the upregulated trend of AQP3, and jointly plays a regulatory role in constipation." (PMID 32774435, 2020). "Among them, AQP3 is the most important aquaporin in the colon, which is closely related to chronic constipation." (PMID 32774435, 2020). "It was also shown that an increase in the expression level of AQP3 is involved in onset of morphine-induced constipation." (PMID 27447626, 2016). "The regulation of AQP-3 expression by plant and food extracts is predicted to relieve constipation." (PMID 41227770, 2025). "However, mulberry (Morus atropurpurea) fruit had a protective effect against diphenoxylate-induced constipation through modulation of gut microbiota and decreased expression of AQP3, AQP4, AQP8, and AQP9 in the colon of mice." (PMID 38089478, 2023). "Thus, we investigated the effect of BCE on the expression of AQP3 and C-kit in the colons of Kunming mice with loperamide-induced constipation." (PMID 36582187, 2023). "Notably, the use of diphenoxylate at much higher dosage for a long time would result in an opposite result, with colonic AQP3 expression downregulated in these constipation models." (PMID 38089478, 2023). "The protein expression of AQP3 and C-kit in the colon of loperamide-induced constipation mice." (PMID 36582187, 2023). "Notably, increasing data has indicated important relationship between AQP3 and prostaglandin E2 during the treatment of constipation." (PMID 38089478, 2023). "Combined with the influence of Bifidobacteria treated by three microencapsulated methods on constipation, Bifidobacteria treated by electrostatic spray drying changed the composition of intestinal microflora, and especially positively correlated with AQP3, but negatively correlated with ET-1 and SS." (PMID 35573767, 2022). "The protein expression analysis showed that AM up-regulated the expression of AQP3 in LOP-induced constipation mice, which indicated that AM may increase luminal side water content to improve constipation." (PMID 31877639, 2019). "In addition, the up regulation on Aqp3 mRNA were also found in constipation-rats induced by morphine." (PMID 30336596, 2018). "Conversely, other research has demonstrated that probiotic supplementation can increase AQP3 expression in models of constipation, highlighting that AQP regulation may exhibit context‐dependent, bidirectional effects depending on the nature of the gastrointestinal disorder." (PMID 40444121, 2025). "Notably, due to the variations of the constipation model, treatment doses, sampling and analysis strategies, the regulation of other agents for constipation on AQP3 expression may involve different mechanisms." (PMID 38089478, 2023). "Thus, further studies are required to reveal the potential mechanism of specific probiotic, prebiotic and herbal extract treatments on 5-HT4R expression through regulation of gut microbiota and and clarify their interactions with AQP3 regulation for constipation." (PMID 38089478, 2023). "Specially, a mixture of probiotic containing Bifidobacterium breve DM8310, Lactobacillus acidophilus DM8302 and Lactobacillus casei DM8121 at a ratio of 1:1:1 could increase the fecal water content and ameliorate loperamide-induced constipation by regulating AQP3 expression in rat colon." (PMID 38089478, 2023).
Constipation (continued). "The present study innovatively elucidated that the herbal formula SHTC alleviates chemotherapy-induced constipation by concurrently modulating gut microbiota homeostasis and activating the PI3K/AKT/AQP3 signaling pathway." (PMID 40708926, 2025). "The transcription levels of AQP3 and AQP8 genes were decreased in both constipation models treated with the Vehicle." (PMID 41011160, 2025). "In human, the expressions of AQP3 and AQP8 were upregulated in patients with constipation, whereas the expressions of AQP1, AQP7, and others were downregulated." (PMID 40807605, 2025). "In addition, considering that SHTC significantly increases the level of acetic acid, we query whether SHTC plays a regulatory role in the activation of PI3K/AKT/AQP3 pathway via alternating the production of acetic acid, which further improved 5-FU induced constipation." (PMID 40708926, 2025). "Treatment with Urd increased the transcription of AQP3 7.4 times and 5.8 times for AQP8 in the C3 KO model compared to the Lop-induced constipation model." (PMID 41011160, 2025). "Clone aquaporins, particularly AQP3 and AQP4, play crucial roles in water transport and are potential targets for constipation prevention." (PMID 41517161, 2025). "In the rat constipation model, the expression of AQP8 was increased in the colon, while increased AQP3 expression was increased at the proximal but decreased at the distal." (PMID 40807605, 2025). "PKA, AQP3, and AQP8 expression was increased by constipation induction; however, lactitol treatment decreased their expression in a concentration-dependent manner." (PMID 38998634, 2024). "In this study, the mRNA expression levels of AQP3 and AQP8 were decreased in the colonic mucosa in loperamide-induced constipation rats, and rifaximin significantly increased the expression of AQP3 and AQP8." (PMID 37960154, 2023). "In this study, to elucidate the mechanism by which the water‐soluble dietary fiber PHGG improves constipation, we investigated the action of PHGG on defecation status, focusing on the colonic water channel AQP3." (PMID 36789055, 2023). "Another study also indicated that the yellow tea extract consumption protected against operamide-induced constipation in mice partially through the upregulation of 5-HT3 and 5-HT4 expression and downregulation of AQP3 and AQP4 expression in the colon." (PMID 38089478, 2023). "Current progress has indicated that AQP3 may act an important target for the disorders that involve disruption of intestinal fluid homeostasis (created with BioRender.com), such as diarrhea, constipation, inflammatory bowel disease, and irritable bowel syndrome." (PMID 38089478, 2023). "In this study, we investigated the role of aquaporin‐3 (AQP3), which regulates the water content of feces in ameliorative effect of PHGG on constipation." (PMID 36789055, 2023). "In this study, we found that QCT can downregulate the expressions of AQP3 mRNA and protein via VIP‐cAMP‐PKA‐AQP3 signaling pathway, which prevent the reabsorption of water in the lumen by blood vessels, thus improving constipation." (PMID 34136194, 2021). "In this study, the expression level of AQP3 and AQP8 was detected and the results showed that YTC decreases the expression of AQP3 and AQP8 in the colons of mice with diphenoxylate-induced constipation." (PMID 32148532, 2020). "The results suggest that YTC decreases the expression of AQP3 and AQP8 in the colons of mice with diphenoxylate-induced constipation." (PMID 32148532, 2020). "Emerging evidence indicates that dysregulated expression of colonic aquaporins (e.g., AQP3 and AQP4) may lead to excessive colonic water absorption and/or reduced secretion of intestinal fluid, thereby contributing to the pathogenesis of constipation." (PMID 41154071, 2025).
Constipation (continued). "Rats fed with bacterial cellulose, a naturally occurring DF derived from bacteria, improved constipation symptoms, shortened defecation periods, increased feces weight, and decreased levels of inhibitory neurotransmitters and AQPs (AQP2, AQP3, and AQP4) in comparison to the constipation group." (PMID 40807605, 2025). "In a rat model of loperamide-induced constipation, probiotic administration increased the fecal water content and intestinal motility by modulating gastrointestinal peptides such as motilin, vasoactive intestinal peptide (VIP), and AQP3." (PMID 38612481, 2024). "Surprisingly, in mice colon with loperamide-induced constipation, the flavanone naringenin was found to upregulate AQP3 mRNA and protein expression, as opposed to the effect of daiokanzoto and RFP, but also causing an increase in fecal water content." (PMID 35187089, 2022). "Thus, we designed to examine the effect of YTC on the expression of AQP3 and AQP8 in the colons of mice with diphenoxylate-induced constipation." (PMID 32148532, 2020). "In agreement with the mRNA expressions, western blot analysis showed that the protein level of AQP3 was significantly increased in the colon of LOP-induced constipation mice by 30.9% (p < 0.001) compared with the normal group." (PMID 31877639, 2019). "However, fructose treatment did not significantly affect the AQP3 protein expression in the colon of rats compared to those in the constipation model group." (PMID 38089478, 2023).
hepatocellular carcinoma (25 papers, 2013 to 2025). A malignant tumor that arises from hepatocytes. "In this regard, functional AQP3 and Nek2 is mutated or highly expressed in hepatocellular carcinoma, these molecular and cellular mechanisms may be overcome by the pharmacological action of AQP3/STAT3/CD133 pathway degradation and Nek2 inhibition." (PMID 35820920, 2022). "Next, whether AQP3 acted as an oncogenic gene in HCC and maintained the stemness of CD133+ hepatoma cells were elucidated; also, a novel mechanism underlying the AQP3/STAT3/CD133 pathway in HCC was deduced." (PMID 31197130, 2019). "Auphen was reported to exert a therapeutic effect in several pathologies, including hepatocellular carcinoma and inflammation, where AQP3 plays an important role." (PMID 39941100, 2025). "The correlation of AQP3 and AQP5 with EMT and tumorigenesis has also been reported in triple-negative breast cancer and hepatocellular carcinoma patients, suggesting the potential of AQP3 and AQP5 as prognostic and therapeutic markers." (PMID 39941100, 2025). "In hepatocellular carcinoma, miR-124 can decrease AQP3 expression, inhibiting cell proliferation and migration, while miR-1271-5p can prevent hepatitis B-virus-mediated liver cancer growth in vivo by decreasing the expression of AQP5." (PMID 39941100, 2025). "AQP3 promotes stem cell-like properties by regulating AQP3/STAT3/CD133 expression in hepatocellular carcinoma cells." (PMID 39611488, 2025). "In HCC, AQP3 is often overexpressed, leading to the promotion of stem cell-like properties in hepatoma cells by regulating CD133." (PMID 37508353, 2023). "Auphen was also shown to inhibit AQP7 in adipocytes and was used to unveil a role of AQP3 in keratinocytes autophagy, to suppress growth of hepatocellular carcinoma by downregulating AQP3, and to impair cell migration via AQP3 blockage in colonic epithelia." (PMID 35187089, 2022). "The gold (III) compound Auphen is an aquaporin inhibitor of AQP3, AQP7, and AQP9 and was efficacious in treating hepatocellular carcinoma by regulating AQP3 expression." (PMID 36212456, 2022). "In the present study, we proved the carcinogenesis roles of aquaporin 3 (AQP3) in hepatocellular carcinoma (HCC) and demonstrated that AQP3 promotes the stem cell-like properties of hepatoma cells by regulating CD133 expression." (PMID 31197130, 2019). "Further investigations revealed that AQP3 promotes the stem cell-like properties of hepatoma cells by regulating the expression of CD133." (PMID 31197130, 2019). "AQP3 is upregulated in cutaneous, esophageal and oral squamous, pulmonary, renal, or hepatocellular cancers." (PMID 30555637, 2018). "Through an independent secondary study with qRT-PCR analysis, we confirmed that AQP3 mRNA levels increase in P. berghei-infected HepG2 and HuH7 hepatoma lines." (PMID 29775485, 2018). "However, further investigation is necessary to elucidate the precise regulation of AQP3-mediated autophagy by hepatocellular carcinoma ECM and its therapeutic implications for overcoming chemoresistance." (PMID 40161518, 2025). "Furthermore, this study demonstrates that TPGS-FA/NC suppresses hepatoma cell proliferation and hepatic CSCs, as well as the AQP3/STAT3/CD133 axis and Nek2 expression in offering possible multiple mechanisms for its antitumor activity." (PMID 35820920, 2022). "For example, circHIPK3, as a sponge of miR-124, could upregulate miR-124 target AQP3 expression in hepatocellular carcinoma." (PMID 31346335, 2019). "In hepatocellular carcinoma (HCC), AQP3 was upregulated, and AQP7 and AQP9 were downregulated, being significantly associated with the aggressive features of HCC." (PMID 35187089, 2022). "In addition, AQP3, 5, 8, and 9 might be potential biomarker for several cancers of the digestive system namely colorectal, gastric, esophageal, and hepatocellular cancers." (PMID 33796134, 2021).
hepatocellular carcinoma (continued). "Similarly, AQP3 is highly expressed in hepatocellular carcinoma (HCC), where it correlates with advanced stage, metastasis, and poor prognosis." (PMID 40806720, 2025). "In hepatocellular carcinoma (HCC), circHIPK3 acts as a miR-124 sponge and regulates the expression of the miR-124 target gene aquaporin 3 (AQP3)." (PMID 36494488, 2022). "A study showed AQP3 localized in the PVM, facilitated the transport of water and glycerol to Plasmodium, and identified it as essential to parasite development in hepatoma cells." (PMID 33796134, 2021). "AQP3 and AQP5 overexpression indicates a poor prognosis and low 5-year survival rates for patients with hepatocellular carcinoma." (PMID 30555637, 2018). "Similarly, both AQP3 and AQP7 are found in both the nucleus and cytoplasm of hepatocellular carcinoma." (PMID 33917751, 2021).